LEPR (leptin receptor)
Diseases named in the same sentence as LEPR in open-access papers (continued):
Sharing a sentence is not in itself a finding about the gene and the disease.
Obesity (continued). "In addition, the effect of serum leptin concentration and leptin receptor expression on clinical and pathological parameters such as BMI, obesity, TNM and tumor size was assessed." (PMID 36981858, 2023). "Some in vitro studies showed that chemical chaperones and a newly FDA-approved drug, Setmelanotide (an MC4R agonist), could be used to treat some monogenic forms of obesity due to POMC, PCSK1, or LEPR deficiency." (PMID 38003551, 2023). "Given that hypothalamic Slug is upregulated in obesity, we postulated that aberrant Slug might increase LepR promoter H3K27me2/3 levels in diet-induced obesity." (PMID 36512408, 2023). "In addition, our ethnically homogeneous study unambiguously shows that the onset of severe obesity is ∼3 years earlier in both LEP and LEPR deficiencies compared with the children deficient for MC4R." (PMID 37659411, 2023). "Ablation of LEPR also in GABA-expressing neurons triggered severe obesity." (PMID 37635967, 2023). "It has been shown that leptin-deficient and leptin-receptor deficient mice were shown to have increased bone formation, suggesting the negative effect of increased leptin in obesity on bone formation." (PMID 36926024, 2023). "An important consideration for the development of therapeutic LepR agonists is that the serum levels of endogenous leptin are highly elevated in the context of human obesity, ranging from 5 ng/ml (0.3 nM) in lean individuals to as high as 100 ng/ml (6 nM) in obesity." (PMID 37002197, 2023). "Thus, leptin-induced increased LepR expression appears to be restrained during obesity, thereby contributing to a reduction in leptin’s actions." (PMID 36769012, 2023). "These cells play a key role in the control of food intake and energy balance, and the disruption of this circuit by changes in leptin sensitivity or mutations in the genes encoding leptin, the leptin receptor, POMC, or MC4R, amongst other genes in this system, can lead to severe obesity." (PMID 36674935, 2023). "Obesity in Zucker fatty rats due to a mutation in the leptin receptor gene does not properly model common obesity in humans." (PMID 36992680, 2023). "Leptin receptor null rats display obesity, hyperphagia, glucose intolerance, and hyperlipidemia." (PMID 35681388, 2022). "The concept of leptin resistance may explain the paradoxically elevated leptin levels in obesity, notably through impaired transportation of leptin through the blood-brain barrier and the decreased hypothalamic leptin receptor expression." (PMID 35334929, 2022). "In this model, obesity can be induced by a mutation in the leptin receptor gene (db/db mouse) or by the lack of leptin (the ob/ob mouse), both causing the mice to overfeed." (PMID 35164764, 2022). "Such genetic variants in the leptin-melanocortin signaling pathway are the cause of rare genetic diseases of obesity, including proopiomelanocortin (POMC) deficiency and leptin receptor (LEPR) deficiency, which are characterized by early-onset severe obesity and hyperphagia." (PMID 35123544, 2022). "Thus, this study aimed to examine the associations between FTO (rs9939609), FABP2 (rs1799883), LEP (rs2167270), LEPR (rs1137101), and MC4R (rs17782313) polymorphisms and obesity-related traits." (PMID 35627568, 2022). "Excess circulatory leptin levels, along with defective leptin receptor signaling, could lead to leptin resistance, which further aggravates obesity, allowing for the initiation of a vicious positive feedback loop." (PMID 35628271, 2022). "Our results demonstrated that obesity with leptin deficiency or leptin receptor deficiency does not stimulate endometriosis development." (PMID 36140261, 2022). "Many studies have shown that LEP and LEPR play an important role in obesity." (PMID 36253742, 2022).
Obesity (continued). "The compound heterozygous carriers of pathogenic genetic variants in the autosomal recessive genes LEP, LEPR, POMC and PCSK1 are rare, obesity-associated variants in the autosomal dominant gene MC4R are the most common, with 0.8% of participants in our study carrying a variant in MC4R." (PMID 35574020, 2022). "The relationship between leptin, leptin receptor and obesity." (PMID 36551995, 2022). "Obesity-induced increases in serum leptin levels have also been shown to skew bifurcation of leptin receptor (LEPR) expressing skeletal stem/progenitor cells (SSPCs), which function as precursors of bone and fat in adult bone marrow, toward adipogenesis at the expense of osteogenesis." (PMID 36138736, 2022). "The discovery that leptin receptor deficient db/db mice have less CTR expression in the AP adds to these findings, but they cannot easily be translated to humans because primary leptin receptor deficiency is not the cause of common obesity." (PMID 35456307, 2022). "ZDF rats are homozygous for a non-functional leptin receptor which causes obesity and insulin resistance." (PMID 36389223, 2022). "Therefore, this study aimed to analyze associations between FTO (rs9939609), FABP2 (rs1799883), and LEP (rs2167270), LEPR (rs1137101), and MC4R (rs17782313) polymorphisms and obesity-related parameters." (PMID 35627568, 2022). "This may be because db/db mice as transgenic rodent is completely resistant to leptin receptor, developed morbid obesity and severe systemic metabolic phenotype at 20 weeks of age which is irreversible by SPRC treatment." (PMID 34604360, 2021). "CHH patients may occasionally display a mild obese phenotype; however, patients affected by normosmic CHH and severe early-onset obesity harbor pathogenic variants in LEP (chr 7q31.3) and LEPR (chr1p31) genes." (PMID 34502334, 2021). "In db/db mice, defined by the deletion of the leptin receptor, there is uncontrolled food intake, obesity, hyperglycemia, insulin resistance, and the development of type 2 diabetes mellitus along with pathological complications, in particular, neurodegeneration and cognitive impairment." (PMID 34685538, 2021). "Similarly, knockdown of Leptin receptor positive NPY/AgRP/GABA neurons in the ARC cannot fully explain the effects of leptin on dietary intake since only mild obesity also results in such mice." (PMID 33679451, 2021). "Nevertheless, it should be remembered that Zucker rats used in the experiment were not healthy: leptin receptor mutation evokes many disorders in itself, not only obesity." (PMID 33833309, 2021). "A study in adults undergoing weight-loss treatment programs showed associations between food craving, overeating, and genetic polymorphisms involved in addiction, as well as a significant gene-gene interaction between DRD2 and LEPR, which synergistically influences the development of severe obesity." (PMID 35127598, 2021). "Chronic protocols could show more long-term beneficial effects of leptin receptor blockade on blood pressure and/or highlight the detrimental effects of leptin inhibition on obesity and SDB." (PMID 34276408, 2021). "We suggest that LEP/LEPR heterozygosity may dispose to overweight and obesity particularly in adulthood, and together with obesogenic factors, it may contribute to the development of obesity." (PMID 34448070, 2021). "Both the LEPR gene variant (rs1137101) and the BDNF gene variant (rs925946) showed strong association with obesity in the association analysis, as indicated by the beta values (1.068 (0.360; 1.777I), p = 0.003; and 1.237 (0.414; 2.059), p = 0.003, respectively)." (PMID 34685457, 2021). "Currently described non-syndromic forms of mendelian obesity comprise mainly genetic defects in the leptin/melanocortin pathway, such as mutations in the genes encoding LEP, LEPR, prohormone convertase 1 (PC1/3), proopiomelanocortin (POMC) and melanocortin receptor 4 (MC4R), leading to overeating." (PMID 33800718, 2021).
Obesity (continued). "Although several genetic analyses continue to provide evidence regarding the polymorphism that compromises the LEP/LEPR axis in an obesity setting, there are no comprehensive studies exploring the effects of SNPs on EE and thermoregulation." (PMID 34208585, 2021). "In one study on binge-eating in severe obesity associated with MC4R and LEPR variants, it was observed that prevalence of binge-eating in LEPR heterozygous variant carriers, including p.R612H variant, was higher than in controls, but no individual cases were reported." (PMID 34448070, 2021). "POUND mice were used as a model for obesity, they have a deletion mutation in exon two of the leptin receptor gene on chromosome four, resulting in it lacking the leptin receptor." (PMID 34445503, 2021). "This anorectic profile has been reported to be associated with lower hypothalamic activity of the protein tyrosine phosphatase 1B (PTP1B), a major negative regulator of leptin receptor signaling in obesity, and with increased activation of leptin receptor downstream signals." (PMID 33741533, 2021). "Several potential obesity candidate genes and variants have been documented, including LEP and LEPR, which have been mainly implicated in monogenic obesity, as well as FTO, APOE, PPARG, and PPARA which have been mainly implicated in polygenic/common obesity." (PMID 34131278, 2021). "Setmelanotide is prescribed for the treatment of rare genetic diseases of obesity caused by certain variants of the genes encoding for pro-opiomelanocortin (POMC), proprotein convertase subtilisin/kexin type 1 (PCSK1), or leptin receptor (LEPR) all of which cause a deficiency of these molecules." (PMID 33670364, 2021). "Indeed, studies in consanguineous families led to the discovery of the first homozygous loss-of-function mutations in the genes encoding leptin (LEP;) and the leptin receptor (LEPR;) associated with severe obesity." (PMID 34748544, 2021). "109Lys>Arg LEPR gene polymorphism correlates with obesity in healthy women but does not increase the risk and stage of breast cancer." (PMID 33864589, 2021). "Single nucleotidepolymorphism (SNP) in the leptin and leptin receptor(LEPR) have been studied as factors that may be associated with PCOS and obesity, which is reported in morethan half of the women with PCOS." (PMID 33687165, 2021). "An agonist of the MC4R, used in individuals with severe obesity due to either POMC, PCSK1, or LEPR deficiency, and should not be used for other types of obesity such as general obesity." (PMID 34552557, 2021). "Unlike other common models of obesity such as the leptin-deficient ob/ob or leptin-receptor deficient db/db mice, Ay/a mice express both a functional leptin gene and a leptin receptor." (PMID 34604220, 2021). "The observation that IL-33 increases the expression of the leptin receptor in some cell types also suggest that there might be differences in the role of IL-33 in db/db mice versus mice with other forms of obesity." (PMID 32326950, 2020). "Moreover, CRP can be stimulated by leptin levels and CRP seemed to bind leptin receptor exerting modulations in both adipose tissue physiology as well as pathogenesis of obesity-related diseases." (PMID 32610476, 2020). "As well, very recent studies suggest that CRP is not only capable of binding to leptin but may compete with it for binding to the leptin receptor, which may lead to leptin resistance and, as a result, obesity." (PMID 32027700, 2020). "Moreover, obesity is characterized by diminished leptin receptor signaling, designated as leptin resistance." (PMID 33396484, 2020). "Mutations in genes that have a physiological role in the hypothalamic leptin–melanocortin energy balance system, such as mutations in leptin, leptin receptor, POMC, prohormone 1/3 convertases (PC1/3), MC4R, are related to the currently known monogenic forms of obesity." (PMID 33261141, 2020).
Obesity (continued). "Apart from the hyperglycemia, the db/db mice due to the leptin receptor defect have pronounced obesity which may also contribute to these alterations." (PMID 32655412, 2020). "Some of the genes associated with monogenetic severe obesity are: leptin (LEP), leptin receptor (LEPR), proopiomelanocortin (POMC), MC4R, preproconvertase 1 (PCSK1), single minded 1 (SIM1), brain-derived neurotrophic factor (BDNF), and tyrosine kinase receptor tropomycin-related kinase B (TrkB)." (PMID 32982666, 2020). "Although leptin receptor antagonist therapies are still undergoing clinical trials, leptin is still considered a candidate cancer treatment due to its unique status as a link between obesity and cancer." (PMID 32836215, 2020). "In addition to the genetic effect of LEPR rs8179183, an individual’s metabolic health status influences several obesity-related metabolic traits." (PMID 32517169, 2020). "Generally, mutations in leptin (LEP), the leptin receptor (LEPR) and the melanocortin 4 receptor (MC4R) represent the most common cause of monogenic forms of obesity and mutations within these genes have been demonstrated to cause childhood morbid obesity in probands of various ethnicities." (PMID 31488071, 2019). "That is, as obesity increases, the likelihood of desensitization of the leptin receptor increases." (PMID 31703113, 2019). "Taken together our results suggest that obesity-related hyperleptinemia may contribute to autophagy activation in adipose tissue, acting in an autocrine/paracrine manner via the leptin receptor." (PMID 30676227, 2019). "Firstly, db/db mice, as the model of type 2 DN with significant hyperglycemia and insulin resistance, are the excellent obesity model with the leptin receptor gene mutation, whose renal lesions is not severe." (PMID 31632286, 2019). "LepR reactivation before the onset of obesity confirmed the energy imbalance of Ubi-LepRNull mice." (PMID 30694175, 2019). "Lack of LEP‐mediated signaling (mutation in LEP or LEPR) leads to the increased tendency of food uptake, severe obesity, hypothyroidism, and infertility." (PMID 31070016, 2019). "Celastrol does not have anti-obesity effects in leptin receptor mutant mice (db/db), and has minimal effect in leptin-deficient (ob/ob) obesity models." (PMID 31488870, 2019). "The study showed that parental obesity was associated with significantly higher serum levels of FABP4 and leptin receptor in their offspring, whereas parental DM was linked to lower adiponectin but higher retinol binding protein 4 concentrations in the offspring." (PMID 30818771, 2019). "Thus genetic screening of consanguineous families with severe early-onset obesity, constitutes a powerful method of identifying causal homozygous mutations and has enabled the identification of rare damaging variants in e.g. LEP, LEPR and MC4R." (PMID 31488071, 2019). "Moreover, this adipokine is expressed in the fetal side of the placenta greater than in the maternal side, being associated with a higher level of leptin promoter methylation and with a lower expression of the leptin receptor in pregnant women with obesity." (PMID 31794592, 2019). "The discrepancy between the increased leptin receptor expression in obesity and the altered functionality in NK cells after leptin incubation could be explained by an impaired post-receptor leptin signaling cascade in NK cells." (PMID 29560551, 2018). "Therefore, Y123F mice are more suitable to be a new animal model to investigate the role of leptin and lepR in reproduction, especially in obesity-related infertility." (PMID 29728128, 2018). "Since obesity and obesity-related infertility/subfertility are growing problems in human beings, our finding that direct effects of leptin and lepR on ovary were involved in infertility of Y123F mice, suggested a new viewpoint on the relationship between obesity and reproduction." (PMID 29728128, 2018).
Obesity (continued). "Also, leptin and leptin receptor gene defects result in human obesity and delayed puberty, oligo-anovulation, or subfertility in most human populations." (PMID 29728128, 2018). "The aim of the present study was to assess the independent contributions of LEPR (rs1137101), FTO (rs9939609), MC4R (rs2229616 and rs17782313), and PPARG-2 (rs1801282) polymorphisms for clinically overweight or obesity phenotypes and endocrine-metabolic traits in prepubertal children." (PMID 29679223, 2018). "LEPR rs6588147 was associated with obesity among women (OR = 1.12, 95% CI: 1.03–1.22) but not among men." (PMID 30379922, 2018). "Although several independent studies identified significant associations between genetic variants of LEPR and obesity, others did not." (PMID 29293570, 2018). "The observation that hyperleptinemia per se, and thus chronically higher LEPR signaling, is upstream of leptin resistance in obesity could imply a pharmacological ceiling effect." (PMID 29748097, 2018). "Prenatal deletion of LepR in POMC neurons does not affect food intake or energy expenditure but causes obesity and reduces Pomc expression." (PMID 30304668, 2018). "An even stronger decrease in cardiac UCP3 content was observed in the LoxTB MC4R−/− mice (28–34% decrease) and LepR/Nestin-cre mice (38–40% decrease), two other models of type 2 diabetes which are also characterized by severe obesity, insulin resistance, hyperinsulinemia, and glucose intolerance." (PMID 30374710, 2018). "Studies on the leptin receptor (LEPR) have advanced the comprehension of the mechanism for regulating body weight and energy homeostasis and have shown that LEPR may influence the onset of obesity, T2DM, and other complex defects such as MetS." (PMID 30583468, 2018). "Obesity is a major risk factor for development of T2D, and lacking of leptin or the leptin receptor (LepRb/ObRb) will develop severe obesity and insulin resistance." (PMID 30115855, 2018). "To understand features of human obesity and type 2 diabetes mellitus (T2D) that can be recapitulated in the mouse, we compared C57BL/6J mice fed a Western-style diet (WD) to weight-matched genetically obese leptin receptor-deficient mice (db/db)." (PMID 29038790, 2017). "Significant associations observed for the leptin receptor (LEPR) gene and angiotensinogen (AGT) gene polymorphisms with obesity and hypertension, respectively, supported the notion that the prevalence of high-risk alleles increased with adaptation to an island environment." (PMID 28253292, 2017). "A GWAS which identified 14 known obesity susceptibility variants and 18 new loci that were associated with BMI found that some of these loci are mapped at the LEP–POMC pathway, i.e., LEP and its receptor LEPR, POMC and MC4R." (PMID 28615046, 2017). "The first of these studies reported that obesity, diabetes, and infertility in Lepr-null db/db mice could be rescued completely by re-introducing neuron-specific LEPR-B transgenes to restore LEPR function selectively in the neurons." (PMID 29354094, 2017). "The remarkable magnitude and rapid occurrence of beta cell proliferation in LepR-KO mice was far greater than observed in previous models, hinting that obesity-induced beta cell proliferation might exceed the limitations of the refractory period." (PMID 27003683, 2016). "Therefore, the purpose of this study was to investigate the effects of hypoxic living and exercise training on obesity and adipose tissue leptin/leptin receptor in dietary-induced obese rats." (PMID 27932989, 2016). "We noticed that the most frequent genotypes in obese children were AG+GG for LEPR 223 gene (P = 0.0001) and GA+AA for LEPR 1019 gene (P = 0.0001), whereas LEPR 492 and LEPR 976 gene polymorphisms did not correlate with obesity." (PMID 27015185, 2016). "Whereas leptin receptor-deficient (db/db) mice develop obesity, hyperglycemia, and dyslipidemia without hypertension." (PMID 27708685, 2016).